FGF21 (fibroblast growth factor 21)
Diseases named in the same sentence as FGF21 in open-access papers (continued):
Sharing a sentence is not in itself a finding about the gene and the disease.
cardiovascular diseases (continued). "Recently, more and more clinical evidence has demonstrated that FGF21 is a prognosis biomarker for relevant cardiovascular diseases for its paradoxical upregulation expression during the onset stage of disease." (PMID 35463746, 2022). "Except for protective effects in cardiovascular disease, high FGF21 levels can predict the incidence of coronary artery disease as well." (PMID 35677107, 2022). "FGF21 works as a protective factor in cardiovascular diseases such as atherosclerosis, cardiovascular endothelial injury caused by oxidative stress, and diabetic heart disease." (PMID 35677107, 2022). "In one clinical study, FGF21 is found abundantly secreted into the plasma in response to cardiac stress stimuli in patients with cardiovascular diseases." (PMID 36180826, 2022). "In patients with cardiovascular disease, circulating FGF21 concentration is closely related to prognosis." (PMID 35369322, 2022). "Given that FGF21 shows beneficial effects in cardiovascular disease, we first examined the expression level of FGF21 in HPH mice." (PMID 35437883, 2022). "Recent studies have shown that FGF21 plays a vital role in the onset and development of cardiovascular diseases." (PMID 34630093, 2021). "As such, FGF21 therapy has been studied as a treatment against cardiovascular disease, in which improvements of adipogenesis, glucose regulation, and lipid metabolism have been previously reported." (PMID 34019585, 2021). "The expression of FGF21 increases due to stimulation by inflammation, oxidative stress, lipid toxicity and endoplasmic reticulum stress, which plays an important role in cardiovascular disease." (PMID 34703671, 2021). "There is a growing consensus that the mechanism of FGF21 in the prevention and treatment of cardiovascular diseases is related to ER stress and oxidative stress." (PMID 34777697, 2021). "We and other groups previously showed that circulating FGF21 levels were increased in patients with cardiovascular disease." (PMID 33073318, 2021). "There is indirect evidence that FGF21 is involved in cardiac remodeling and can be a therapeutic target in both metabolic and cardiovascular diseases." (PMID 34573919, 2021). "Fibroblast growth factor 21 (Fgf21) is an important endocrine factor, which has been shown to play an important role in cardiovascular diseases." (PMID 34708083, 2021). "Previous small studies have reported an association between circulating fibroblast growth factor 21 (FGF21) levels and pericardial fat volume in post-menopausal women and high cardiovascular disease (CVD) risk patients." (PMID 31712677, 2019). "The relationship between fibroblast growth factor 21 (FGF21) and cardiovascular disease has been well established in recent studies." (PMID 28821258, 2017). "Fibroblast growth factor-21 (FGF21) is closely related to various metabolic and cardiovascular disorders." (PMID 27387420, 2016). "Recently, several reports have examined the role of FGF21 in cardiovascular diseases (CVD) in humans." (PMID 26047614, 2015). "The physiological and pathological significance of increasing serum FGF-21 levels in cardiovascular disease remains to be elucidated." (PMID 21206918, 2010). "PF-05231023 effectively improved the lipid metabolism of Apoe−/− mice, demonstrating an anti-atherosclerotic effect and providing a scientific basis and experimental foundation for the clinical treatment of cardiovascular diseases by using long-acting FGF21 analogs." (PMID 39144082, 2024). "However, it has not been reported which transcription factors regulate the hepatic expression of FGF21 in cardiovascular disease models such as MI." (PMID 37018396, 2023). "In addition, FGF-21 is described as mediating reduced inflammatory oxidative stress in cardiovascular diseases (CVD) by targeting SIRT1." (PMID 37239098, 2023). "The role of fibroblast growth factor 21 (FGF21) in predicting the long-term prognosis of patients with cardiovascular disease (CVD) remains unknown." (PMID 36926038, 2023).
cardiovascular diseases (continued). "Fibroblast growth factor 21 (FGF21) is a novel hepatokine involved in regulating glucose and lipid metabolism, and has been linked to the prediction, treatment, and improvement of prognosis in multiple cardiovascular diseases (CVDs)." (PMID 38057786, 2023). "FGF21 has been previously demonstrated to exert protective effects against cardiovascular diseases." (PMID 37018396, 2023). "Recently, mounting studies have reported the protective role of FGF21 in cardiovascular diseases." (PMID 35437883, 2022). "The elevated levels of FGF21 are closely associated with the increased of inflammation in the body, which may be the reason why elevated FGF21 always means poor prognosis in cardiovascular diseases." (PMID 35369322, 2022). "The effect of FGF21 to cardiovascular diseases is still unclear." (PMID 36180826, 2022). "The role of FGF21 in cardiovascular disease has also been discovered in recent years." (PMID 35369322, 2022). "This suggests an altered FGF-21 signaling during cardiovascular disease, which might also occur in sCVD patients." (PMID 36479354, 2022). "In human, the relationship between FGF21 and cardiovascular disease has been well established." (PMID 35145478, 2021). "However, the increase in FGF21 levels, which has a cardioprotective effect, is negatively correlated with the prognosis of cardiovascular disease." (PMID 34703671, 2021). "However, people with cardiovascular diseases have increased resting concentrations of circulating FGF21, suggesting either a compensatory cardioprotective effect of FGF21 or FGF21 resistance in cardiovascular disease states." (PMID 32156043, 2020). "Circulating FGF21 has been found to be positively associated with carotid intima-media thickness, independent of the well-established risk factors of cardiovascular diseases." (PMID 30185439, 2018). "FGF21 was presented as a potential biomarker for cardiovascular diseases." (PMID 28821258, 2017). "Several recent reports examined the role of FGF21 in cardiovascular diseases." (PMID 26594197, 2015). "Moreover, serum FGF21 levels have also increased in patients with cardiovascular diseases." (PMID 39108652, 2024). "The increased FGF-21 and reduced adiponectin level, along with oxidative stress and inflammation in vitamin D-deficient newly diagnosed T2DM subjects, could further increase the cardiovascular disease risk in them." (PMID 39544568, 2024). "Similarly, other studies found that FGF-21 signaling is affected during cardiovascular disease." (PMID 36479354, 2022). "In addition, FGF21 also plays a critical role in the treatment of cardiovascular diseases." (PMID 34349728, 2021). "Furthermore, the utility of this biomarker is enhanced by the fact that FGF21 could be used in the future as a target therapy in metabolic and cardiovascular disease." (PMID 34573919, 2021). "In this present study, elevated circulating FGF21 levels were significantly associated with elevated pericardial fat volume cross-sectionally and in a multi-ethnic cohort of adults without a history of clinical cardiovascular disease." (PMID 31712677, 2019). "A prospective cohort study of 1668 CAD patients with a follow-up of approximately 5 years demonstrate that both higher and lower serum FGF21 levels were correlated with higher risks for all-cause mortality, independent of traditional risk factors of cardiovascular diseases." (PMID 30185439, 2018). "However, cardiac stresses may increase serum FGF-21 both in human cardiovascular disease and in animal models of progressive MD." (PMID 28825656, 2017). "Further research is needed to elucidate how FGF21 modulates VSMC behavior and to explore its potential as a therapeutic target for cardiovascular diseases." (PMID 40765997, 2025). "The interest in developing FGF21-mimetics has also led to the recognition of KLB as a promising drug target for treating metabolic and cardiovascular diseases." (PMID 39511582, 2024).
cardiovascular diseases (continued). "Similarly, FGF21 may also be a biomarker for cardiovascular disease." (PMID 35046901, 2021). "In another study, serum FGF21 concentration over 232 pg/ml independently predicted adverse atherosclerotic cardiovascular disease events in non-diabetic population." (PMID 35369322, 2022).
mitochondrial disease (70 papers, 2013 to 2025). "Our results suggest that the combination of neurofilament light chain, fibroblast growth factor 21 and growth and differentiation factor 15 is useful in the diagnostic evaluation of mitochondrial disease." (PMID 33501425, 2021). "We have subsequently compared circulating GDF15 and FGF21 levels in a cohort consisting exclusively of children with a diagnosis of mitochondrial disease which included patients with mutations in both mtDNA and nDNA." (PMID 32397676, 2020). "Recently, GDF15 and FGF21 have been recognized to be more sensitive and specific diagnostic markers for mitochondrial diseases than the lactate to pyruvate (L/P) ratio." (PMID 33264289, 2020). "In the present study we have compared circulating GDF-15 and FGF-21 levels in a cohort consisting exclusively of children with a diagnosis of mitochondrial disease which included patients with mutations in both mitochondrial and nuclear DNA." (PMID 26867126, 2016). "• FGF21/GDF15 efficiently identifies mitochondrial diseases due to mutations in tRNA genes." (PMID 32851462, 2020). "Systemic availability of FGF-21 could play a role in the metabolic alterations that are often are associated with mitochondrial diseases." (PMID 24078096, 2013). "FGF-21 could play a role in the metabolic alterations that are often associated with mitochondrial diseases." (PMID 24078096, 2013). "The response in QFs supports this conclusion: fasting‐related metabokine FGF21 is secreted to blood circulation as part of their ATF5‐driven ISRmt response to mitochondrial disease." (PMID 40681476, 2025). "A correlation between the MD stage assessed by IPMDS and the concentration of particular biomarkers of mitochondrial disease: FGF21, LA, PA, ALA and CK, was also verified." (PMID 38542723, 2024). "While FGF21 is known to regulate cell proliferation, development, pyroptosis, apoptosis, autophagy, and mitochondrial diseases, few studies have investigated its role in regulating mitochondrial dysfunction and ferroptosis in PNI." (PMID 39376607, 2024). "It has been confirmed that translational defects in mitochondrial and nuclear DNA, typically seen in mitochondrial diseases involving skeletal muscle, lead to increased FGF21/GDF15 levels." (PMID 39124668, 2024). "FGF21 was reported as a biomarker with high sensitivity for predicting mitochondrial disease in muscle." (PMID 36915160, 2023). "FGF-21 expression increases in response to mitochondrial disease, oxidative stress, and physical stress, resulting in elevated plasma levels." (PMID 37371508, 2023). "In evidence, combining GDF-15 with gelsolin plasma levels performed even better to differentiate patients with mitochondrial disease than the combination with FGF-21 (AUC 0.94 vs. 0.91)." (PMID 36361969, 2022). "In the PMD group, FGF21 was significantly correlated with International Paediatric Mitochondrial Disease Scale (IPMDS) score." (PMID 35498801, 2022). "In other words, higher level of FGF21 corresponds to greater mitochondrial disease severity (higher IPMDS scores)." (PMID 35498801, 2022). "At the same time, FGF21 has a higher level in patients with mitochondrial diseases affecting skeletal muscle, which can be used as a biomarker for mitochondrial respiratory chain defects in muscles." (PMID 34675822, 2021). "Previous studies have identified a threshold value of 350.0 pg/ml for FGF-21 in mitochondrial disease." (PMID 33501425, 2021). "As non-invasive and economical steps in the diagnosis of a mitochondrial disease, the peptide molecule fibroblast-growth-factor-21 (FGF-21) and growth-differentiation-factor-15 (GDF-15) are established biomarkers." (PMID 34572118, 2021). "Similarities also exist with the stimulation of FGF21 from skeletal muscle during conditions of muscle-specific mitochondrial disease, certain types of exercise, and hyperinsulinemia in mice and humans." (PMID 33762965, 2021).
mitochondrial disease (continued). "We measured serum neurofilament light chain, fibroblast growth factor 21 and growth and differentiation factor 15 in 26 patients with a genetically proven mitochondrial disease." (PMID 33501425, 2021). "As elevation of circulating FGF‐21 had been documented in patients with muscle‐manifesting mitochondrial diseases, we tried to investigate the FGF‐21 level in other severe neurological diseases and found that it was also elevated in DS." (PMID 34379890, 2021). "Elevation of serum FGF‐21 was found in patients with impairment of oxidative phosphorylation in muscle, and thus, FGF‐21 had been proposed as a biomarker for muscle‐manifesting mitochondrial diseases." (PMID 34379890, 2021). "A study has found that FGF21 is significantly related to ocular myopathy (a mitochondrial disease), especially chronic progressive external ophthalmoplegia." (PMID 35004861, 2021). "A recent meta-analysis of the literature which included five randomized controlled trials encompassing 718 FGF21 assessments demonstrated the utility of FGF21 as a promising biomarker for mitochondrial disease diagnosis." (PMID 34572066, 2021). "Fibroblast Growth Factor 21 (FGF-21) has also been reported to be elevated in a range of mitochondrial diseases, particularly in those with muscle involvement." (PMID 32572108, 2020). "Significantly increased FGF21 levels in circulation have been detected in patients with muscle-manifesting mitochondrial diseases, in which case most of the circulating FGF21 arises from the muscle." (PMID 33204460, 2020). "In the past years, serum FGF21 and serum GDF15 have emerged as two promising diagnostic biomarkers for mitochondrial diseases." (PMID 32397676, 2020). "Similar to other studies using PPAR agonists, we observed dose‐dependent increases in serum GDF‐15 and FGF‐21, which have been proposed as biomarkers of mitochondrial disease." (PMID 32107855, 2020). "Altogether these mitochondrial changes resulted in a dramatic increase of FGF21 in muscle and serum (100 fold), its range has been reported in patients with mitochondrial diseases and unhealthy aging." (PMID 31057418, 2019). "Serum fibroblast growth factor 21 (FGF-21) has been suggested as a biomarker for mitochondrial disease." (PMID 30159853, 2018). "FGF21 is a biomarker for mitochondrial translation and mtDNA maintenance disorders, and a stress-induced myokine in mitochondrial diseases." (PMID 30024379, 2018). "Fibroblast growth factor 21 (FGF-21), which has a regulatory role in lipid metabolism, can also be used as a blood serum biomarker for mitochondrial diseases." (PMID 30406383, 2018). "We conclude that urine organic acid test in combination with plasma FGF21 determination are valuable tools in the diagnosis of mitochondrial diseases." (PMID 28287425, 2017). "Other investigators have been able to demonstrate a positive correlation between FGF-21 levels and the Newcastle mitochondrial disease scale for adults (NMDAS) clinical assessment scale." (PMID 28825656, 2017). "Recent work has suggested that fibroblast growth factor-21 (FGF-21) is a useful biomarker of mitochondrial disease (MD)." (PMID 28825656, 2017). "Although this study is limited, we conclude that urine organic acid test in combination with plasma FGF21 determination are valuable tools in the diagnosis of mitochondrial diseases." (PMID 28287425, 2017). "Here we evaluated GDF-15 as a biomarker for mitochondrial diseases affecting children and compared it to fibroblast-growth factor 21 (FGF-21)." (PMID 26867126, 2016). "The elevated levels of FGF21 were observed in people suffering from mitochondrial diseases standing as a novel biomarker of mitochondrial disorders." (PMID 28053691, 2016). "It was shown that FGF21 is a hormone that mediates an adaptive response to starvation and becomes also a long-standing marker of mitochondrial disease in humans." (PMID 28053691, 2016).